NLRC4 (NLR family CARD domain containing 4)
Diseases named in the same sentence as NLRC4 in open-access papers (continued):
Sharing a sentence is not in itself a finding about the gene and the disease.
infection (continued). "However, the role of IL-1R signaling during infection with flagellin-deficient L. pneumophila, which do not activate the NAIP5/NLRC4 inflammasome, has not been investigated." (PMID 23762026, 2013). "Moreover, Nlrc4-/- and Nlrp3-/- macrophages presented similar impaired responses to T. cruzi, underscoring the non-redundant roles played by these inflammasomes during infection." (PMID 38124741, 2023). "We noticed that in Nlrc4-/- and GsdmD-/- neutrophils, citrullination was not fully abrogated, suggesting that minor alternative pathways might also promote histone citrullination upon infection with P. aeruginosa pyroptotic strains." (PMID 35849616, 2022). "Interestingly, T. gondii infection upregulated the expression of NLRC4, NLRP4, NLRP8, NLRP10, NLRP11, NLRP13, and NLRP14 mRNAs at both 4 and 8 h post-infection, but NLRP4, NLRP8, NLRP10, and NLRP11 mRNAs were significantly downregulated at 8 h post-infection compared to that at 4 h post-infection." (PMID 33712075, 2021). "As this pathway is independent of flagellin sensing, NLRP3, ASC, and NLRC4, an unknown upstream sensor and/or adaptor may be involved in caspase-11 activation in response to a translocated bacterial substrate or an endogenous signal induced by infection." (PMID 23762026, 2013). "We observed that ΔospC3 Shigella is significantly attenuated in B6.Nlrc4–/– mice but not in B6.Nlrc4–/–Casp11–/–, indicating by a ‘genetics squared’ analysis that Shigella effector OspC3 inhibits CASP11 during oral mouse infection." (PMID 36645406, 2023). "Using their protocol (3 h infection, no LPS priming), we also found that IL-1β secretion by PAO1 is NLRC4-dependent whereas our protocol (3 h priming, 1 h infection) is NLRC4 independent." (PMID 37730693, 2023). "This suggests that NLRC4—but not NLRP3, Caspase-11 or AIM2—efficiently promotes neutrophil pyroptosis upon infection with P. aeruginosa pyroptotic strains." (PMID 35849616, 2022). "During the chronic stages of infection, NLRP3- but not NLRC4- dependent cell death correlated with the expression of fliF in ST isolated from various organs." (PMID 34864057, 2022). "IRF8 is required for the optimal activation of the NLRC4 (NLR family CARD domain containing 4) and NLRP3 (NLR family pyrin domain containing 3) inflammasome activation after infection with Gram-negative bacteria to initiate inflammatory responses." (PMID 34067819, 2021). "Our collective findings from the infection with WT bacteria suggest that NLRP3, but not NLRC4, plays a major role in inducing caspase-1 activation." (PMID 23357873, 2013). "These resultsdemonstrate that apoptosis can occur in Yp-YopJKIM -infectedmacrophages in the absence of NLRP3, NLRC4 or ASC, consistent with our previousdata showing that macrophage apoptosis during Yp-YopJKIM infection isindependent of caspase-1." (PMID 21533069, 2011). "These discrepancies, i.e., activation or not of NLRC4 along with NLRP3, could be attributed to differences in the infection models, fungal strains, and microbiota composition." (PMID 41249509, 2025). "Interestingly, the first infection with flagellin-mutant bacteria (flaA- thyA) still protected the mice against the second infection with JR32 flaA-, indicating that NAIP5/NLRC4 is not essential for this protection." (PMID 40558085, 2025). "Furthermore, in in vivo infection, the expression of SspH2-EscI, but not SspH2 alone, could inhibit the colonization of recombinant bacteria, suggesting that reduction of bacterial colonization in mice may be due to the activation of NLRC4 inflammasome by EscI in the cytoplasm." (PMID 28468643, 2017). "Indeed, the levels of IL-1Ra were sustained in vitro and through the course of either infection in vivo in C57BL/6 but not Cftr–/– mice and NLRC4, more than NLRP3, contributed to this sustained production." (PMID 26972847, 2016).
infection (continued). "Furthermore, when a higher infection dose of S. Typhimurium at an MOI of 20 is used, NLRC4 activation occurs regardless of S533 phosphorylation, and genetic deletion of PKC-δ does not affect inflammasome activation in response to either S. Typhimurium or S. flexneri." (PMID 41062723, 2025). "Perhaps more importantly, the NLRC4 inflammasome can be activated by substances released by dying cells, such as lysophosphatidylcholine (LPC), and thus activation of this inflammasome is an inevitable result of inflammatory tissue destruction that is not dependent on infection by certain organisms." (PMID 41246319, 2025).
tumor (90 papers, 2012 to 2025). "Loss of tumor NLRC4 expression is associated with impaired T cell and DC immune infiltrates in cancer patients." (PMID 38652550, 2024). "Interrogation of mouse NLRC4 protein expression within the tumor (cytokeratin mask) showed a progressive loss of expression as the tumor grew between 3 and 6 months." (PMID 38652550, 2024). "In an azoxymethane (AOM)-DSS mice model with reduced NLRC4 activity and deficient for caspase-1, a significant increase in tumor development and aggressiveness was observed compared to the increase seen in wild type mice." (PMID 39684769, 2024). "Another report identified a mutation in the LRR domain of NLRC4 that is associated with recurrent fever, skin erythema, and inflammatory arthritis symptoms." (PMID 33494299, 2021). "The role of inflammasome activation in tumor progression is also demonstrated in obese mice, where obesity-associated NLRC4 inflammasome activation in tumor-infiltrating myeloid cells promotes breast cancer progression." (PMID 32733461, 2020). "In other malignancies, NLRC4 suppresses the tumor growth of melanoma by stimulating tumor-associated macrophages and generating protective T cells." (PMID 31242947, 2019). "It was reported Caspase1-deficient and Nlrc4-deficient colon epithelial cells were more resistant to programmed cell death and exhibited increased tumor load compared with wild types." (PMID 28360909, 2017). "It has been demonstrated that mice deficient in NLRC4 develop higher tumor burdens than WT mice when subjected to DSS-induced CRC." (PMID 25071785, 2014). "In prostate cancer, elevated NLRC4 expression has been linked to an increased risk of tumor progression might be because of secretion of IL−1β and IL−18." (PMID 40692785, 2025). "Therefore, the gradual loss of NLRC4 expression in the tumor is associated with cancer progression and seems to be conserved between human and mouse." (PMID 38652550, 2024). "This underlying mechanism may explain our observed strong associations between NLRC4 tumor expression with DC2/DC3 and CD4+/CD8+ T cell infiltration into patient tumors for antigen presentation and tumor killing, respectively." (PMID 38652550, 2024). "Hence, these mechanisms contribute to explaining the association between NLRC4 expression and DC/T cell tumor immune infiltration we observed in patient tumors, which correlates with improved survival." (PMID 38652550, 2024). "Moreover, Nlrc4-deficient mice of AOM/DSS models exhibited increased tumor load but unrelated to inflammation." (PMID 28360909, 2017). "Future studies will be needed to determine whether NLRC4 is activated because of changes in the gut microbiota, endotoxaemia or some tumour-associated protein that act as a homologue to these NLRC4-activating bacterial components." (PMID 27708283, 2016). "Similarly to caspase-1 deficient mice, NLRC4 knockout mice features significantly enhanced proliferation in both steady state and the early phase of inflammation-induced tumor formation." (PMID 23606794, 2013). "Here, we discuss the implications of NLRP3, AIM2 and NLRC4 inflammasomes in both cancer development and tumor suppression as well as the potential for future investigations in this context." (PMID 40692785, 2025). "In obesity-driven breast cancer, NLRC4 inflammasome activation in tumor-infiltrating macrophages enhances ANGPTL4 expression in mammary adipocytes via IL-1β, thereby driving tumor progression and angiogenesis." (PMID 40723247, 2025). "Consistent with the results obtained from our TMAs, patients harboring NLRC4-null tumors (through genetic arm-level deletion) exhibited decreased CD4+ T cell tumor infiltration versus diploid normal tumors (P < 0.01)." (PMID 38652550, 2024). "Patients with high levels of NLRC4 protein expression within the tumor had a better survival compared with those with low expression (HR: 0.44, 95%CI: 0.22–0.79, P = 0.0082)." (PMID 38652550, 2024).
tumor (continued). "This work sheds light on epithelial NLRC4 in providing critical priming signals to improve DC and T cell immune response in humans, thereby eventually sensitizing the tumor to current T cell–centric ICB therapies." (PMID 38652550, 2024). "In patients affected by CRC, the gene expression of NLRC4 resulted in a decrease in the tumor portion compared to the adjacent normal tissue, and its lower expression was related to lymph node metastasis." (PMID 39684769, 2024). "The decreased expression of NLRC4 protein in the bulk tumor and its correlation to poor prognosis in CRC patients is consistent with a previous report." (PMID 38652550, 2024). "An extended analysis of additional type I IFN inducers showed that NLRC4 expression had the highest correlation overall across the various DC subsets and tumor types, followed by IFIH1, RIGI, TMEM173, and finally ADAR." (PMID 38652550, 2024). "We observed that compared with patients with high immune infiltrate (n = 8), patients with low immune infiltrate (n = 82) had concomitant lower expression of tumor NLRC4 (P = 0.004)." (PMID 38652550, 2024). "Finally, we show that the loss of NLRC4 expression in patient tumor tissues may be due to the presence of LPS (expressed by gram-negative bacteria), which specifically abolished NLRC4 expression at the transcriptional level but not that of other NLR family members in human primary cells." (PMID 38652550, 2024). "A role for NLRC4 in the pathogenesis of cancer has also been proposed, albeit limited to studies relying on bulk tumor gene expression analysis and mouse models." (PMID 38652550, 2024). "We show that NLRC4 expression in human tumor cells is sufficient to directly promote DC maturation to secrete IL-12 and IFN-γ in vitro, along with the inflammatory cytokine IL-1β." (PMID 38652550, 2024). "It has been shown that in breast cancer, the NLRC4 inflammation expression is upregulated, triggering inflammation and subsequently inducing tumor invasion." (PMID 37705746, 2023). "In adipocytes, NLRC4 inflammasomes induce tumor infiltration into myeloid cells, and IL-1β promotes vascular endothelial growth factor A (VEGFA) secretion and angiogenesis, thereby driving disease progression." (PMID 37020871, 2023). "Activated NLRC4 inflammasomes from tumor-infiltrating myeloid cells produce IL-1β, which promotes vascular endothelial growth factor A (Vegfa) expression in adipocytes facilitating angiogenesis, a key step in metastasis." (PMID 36932407, 2023). "Most of PRGs displayed higher expression levels in tumor samples compared with normal controls except for AIM2, IL1B, and NLRC4, of which the mRNA expression was decreased in tumor samples." (PMID 37051536, 2023). "The differential expression of NLRC4 has investigated the potential role of NLRC4 in different kinds of tumor types." (PMID 36119049, 2022). "Continuously aberrant activation of chronic inflammation mediated by NLRC4 can promote the malignant progression of tumor cells." (PMID 35928454, 2022). "We confirmed that caspase-1 activity and programmed cell death downstream of the NLRC4 inflammasome increased with tumor malignancy because of Tim-3/Gal-9." (PMID 35216164, 2022). "Aside from their roles involving the NLRC4 inflammasome, NAIPs have also been shown to function as tumour suppressors in CRC." (PMID 34854889, 2021). "Diet-induced obesity results in increased tumor burden in mice, by prompting increased NLRC4-dependent production of IL-1β from tumor-infiltrating macrophages." (PMID 35111698, 2021). "The obese tumor microenvironment induced an increase in the number of tumor-infiltrating macrophages with an activated NLRC4 inflammasome, which further activated IL-1β." (PMID 33987528, 2021). "On a cellular level, cytokines and chemokines are critical for tumor killing, and NLRC4 activation is essential for cytokine and chemokine production in tumor-associated macrophages." (PMID 33494299, 2021).
tumor (continued). "Taken together, this report suggests that P2Y2R activation by ATP induces tumor invasion and angiogenesis through inflammasome activation, specifically by regulating the inflammasome components NLRC4, ASC, and caspase-1." (PMID 32397236, 2020). "Accumulation of tumor-infiltrating macrophages with activated NOD-like receptor C4 (NLRC4) inflammasomes in the obese tumor microenvironment has been linked to increased IL-1β activation." (PMID 33604295, 2020). "Utilizing azoxymethane (AOM)/dextran sodium sulfate (DSS) model, it was shown that NLRC4 knockout mice developed increased tumor volume." (PMID 30631327, 2018). "In the AOM/DSS-induced colorectal cancer model, NLRC4 and caspase-1 KO mice exhibited increased tumor load and tumor number per mice." (PMID 28955343, 2017). "Co-injection of cancer cells with WT BMDM had significantly increased tumour growth relative to mice co-injected with Nlrc4−/− BMDM." (PMID 27708283, 2016). "We compared activation of TLR5 and the NLRC4 inflammasome by these two flagellin fusion proteins, and the anti-tumor immunity of these proteins was evaluated using a mouse cancer model." (PMID 27063435, 2016). "This Vegfa upregulation was dependent on the NLRC4 inflammasome as it was abrogated in tumours from DIO mice where IL-1R signalling was blocked or the NLRC4 inflammasome was missing." (PMID 27708283, 2016). "Additional evidence of the role of NAIP/NLRC4 in the activation of T cells came from an experimental vaccination with irradiated flagellin-expressing tumor cells." (PMID 25071770, 2014). "The tumor suppressor effect of the NLRC4-inflammasome seems to be primarily from NLRC4 expression in epithelial cells." (PMID 24474192, 2014). "A novel set of experiments were performed integrating the activation of TLR5, NAIP5, and NLRC4 by bacterial flagellin into tumor immunotherapy." (PMID 24273542, 2013). "Therefore, altogether, high tumor NLRC4 expression tracks with immune infiltration, including DCs and T cells, independently of tumor IL-18 variation, and this is consistent with better clinical survival of patients." (PMID 38652550, 2024). "Strikingly, only the loss of tumor NLRC4, but not stromal NLRC4, was associated with poor immune infiltration (mainly DCs and CD4+ and CD8+ T cells) and accurately predicted progression to metastatic stage IV and decrease in overall survival." (PMID 38652550, 2024). "Compared with wild-type mice, Nlrc4-/- mice could promote the proliferation of colonic epithelial cells and inhibit apoptosis of tumor cells, thereby promoting tumor formation, suggesting a protective effect of NLRC4 inflammasomes on colorectal carcinogenesis." (PMID 37020871, 2023). "Consistent with our research, NLRC4 could also suppress tumor development while inducing antitumor immunity." (PMID 35928454, 2022). "Moreover, NLRC4/NAIP5 also participated in the antigen recognition of flagellin-expressing tumor cells to facilitate antigen presentation to T cells, thereby activating CD4+ and CD8+ T cells and exerting antitumor effects." (PMID 35928454, 2022). "Regarding the tumor tissues, the higher the level of NLRC4, the higher the immune score was." (PMID 36437954, 2022). "Obesity enhanced NLRC4 expression in tumor-infiltrating CD11b+ cells in breast tumors in mice, resulting in activation of IL-1β, and promotion of disease progression through adipocyte-mediated expression of vascular endothelial growth factor A and angiogenesis." (PMID 35739593, 2022). "CASP8, CASP6, GSDME, NOD1, and GPX4 were significantly upregulated in tumor tissues compared to the normal tissues, whereas IL6, IL1B, NLRP3, and NLRC4 were downregulated, suggesting that pyroptosis-related genes play important roles in tumor progression and prognosis." (PMID 35559014, 2022).